MEMO1 (mediator of cell motility 1)
Description:
May control cell migration by relaying extracellular chemotactic signals to the microtubule cytoskeleton. Mediator of ERBB2 signaling. The MEMO1-RHOA-DIAPH1 signaling pathway plays an important role in ERBB2-dependent stabilization of microtubules at the cell cortex. It controls the localization of APC and CLASP2 to the cell membrane, via the regulation of GSK3B activity. In turn, membrane-bound APC allows the localization of the MACF1 to the cell membrane, which is required for microtubule capture and stabilization. Is required for breast carcinoma cell migration.
Synonyms: C2orf4; MEMO; NS5ATP7; CGI-27
Tractability: PROTAC: ubiquitination databases record sites on it; its protein half-life has been measured.
Gene: Protein-coding gene on chromosome 2 (31,865,060 to 32,011,230, reverse strand). Ensembl gene ENSG00000162959.
Subcellular location (Human Protein Atlas): Vesicles
Pathways (Reactome):
Signal Transduction: ERBB2 Regulates Cell Motility
Gene Ontology:
Molecular function: protein binding
Biological process: regulation of microtubule-based process
Cellular component: cytosol; nucleus
Genetic constraint (gnomAD): Loss-of-function variants: 2 observed, 17.91 expected, observed/expected ratio (o/e) 0.11, 90% interval 0.045 to 0.35. The synonymous counts are far from expectation, so gnomAD's model fits this gene poorly and the ratio says little. Missense variants: 124 observed, 233.39 expected, observed/expected ratio (o/e) 0.53, 90% interval 0.46 to 0.62. Synonymous variants: 56 observed, 83.75 expected, observed/expected ratio (o/e) 0.67, 90% interval 0.54 to 0.83.
Homologues: Orthologues: dog MEMO1 (100% identical), macaque MEMO1 (100% identical), pig MEMO1 (100% identical), mouse Memo1 (99% identical), rat Memo1 (99% identical), rabbit MEMO1 (93% identical), tropical clawed frog memo1 (90% identical), zebrafish memo1 (89% identical), guinea pig MEMO1 (71% identical), Drosophila melanogaster CG8031 (63% identical), Caenorhabditis elegans memo-1 (52% identical).
Diseases named in the same sentence as MEMO1 in open-access papers:
MEMO1 is named in the same sentence as 35 diseases in open-access papers, as found by Europe PMC text mining. Sharing a sentence is not in itself a finding about the gene and the disease. The quoted sentences say what the papers report.
breast carcinoma (17 papers, 2016 to 2025). "Mediator of cell motility 1 (MEMO1) has been implicated in breast cancer metastasis through its interaction with copper ions and subsequent ROS production, although recent evidence suggests it binds more readily to Cu(I), potentially mitigating redox activity." (PMID 38693584, 2024). "In agreement with the previous reports, we found that MEMO1 knockout in breast cancer cells results in the loss of cell motility as assessed by the wound healing assay." (PMID 38640016, 2024). "It is interesting to note however, that in these settings’ loss of MEMO1 was associated with a more oxidized state—contrasting with findings in breast cancer cells." (PMID 33172038, 2020). "Memo1 has been implicated in promoting cell motility and in the proliferation of breast cancer cells, processes which are analogous to events regulated during granule cell development." (PMID 29578408, 2018). "MEMO1, an evolutionarily conserved protein implicated in cancer, binds iron and regulates iron metabolism, thereby influencing tumor cell proliferation, metastasis, and sensitivity to ferroptosis, particularly in breast cancer." (PMID 40278406, 2025). "Interestingly, Memo1 has been linked to NADPH oxidase activity in breast cancer cells, however the exact mechanism underlying these results, as well as a role for RhoA, has not been established and is likely to be context-dependent." (PMID 28085666, 2017). "Measurements of iron concentration in breast cancer cells with varying MEMO1 expression revealed distinct mitochondrial iron levels." (PMID 40278406, 2025). "In this respect, MEMO1 is required for breast carcinogenesis as well as the migration and invasion of breast cancer cells and their metastasis in vivo." (PMID 40721800, 2025). "Based on these findings, we measured the TCA cycle metabolite levels in breast cancer cells with varying levels of MEMO1 expression." (PMID 40278406, 2025). "Further analyses of MEMO1 levels in breast cancer subtypes determined that MEMO1 overexpression is more prominent in triple negative (TNBC) and HER2+ (HER2-enriched) breast tumors than in the luminal subtype." (PMID 38640016, 2024). "Overall, these results indicate that MEMO1 overexpression sensitizes breast cancer cells to ferroptosis." (PMID 38640016, 2024). "Effect of the selected iron-related shRNA gene knockdowns on MEMO1 levels in breast cancer (C) and melanoma (D) cell lines detected by western blot analysis." (PMID 38640016, 2024). "(C) Subtype analysis of MEMO1 expression in breast cancer, including luminal (blue), HER2 positive (green), and triple-negative breast cancer (TNBC, gray)." (PMID 38640016, 2024). "Across the board comparison of MEMO1 GIs and MEMO1 knockout effects between breast cancer and melanoma cells indicate that variations in MEMO1 levels overall have stronger effects in breast cancer cells than in melanoma." (PMID 38640016, 2024). "Treatment with a copper chelator called TTM lowers copper levels, inhibits MEMO1, delays blood vessel formation, and prevents breast cancer metastasis." (PMID 38662225, 2024). "For example, a mediator of cell motility 1 (MEMO1) is a Memo, a Cu-dependent redox protein identified as an intracellular Cu-dependent protein essential for migration and invasion of breast cancer cells in vitro and spontaneous lung metastasis in vivo." (PMID 38883186, 2024). "The MEMO1, another copper-dependent protein, is involved in cell movement and metastasis of breast cancer." (PMID 38662225, 2024). "We have validated GIs between MEMO1 and many genes encoding iron-related proteins by studying the effects of LOF of those gene products on the proliferation of breast cancer and melanoma cell lines with different expression levels of MEMO1." (PMID 38640016, 2024). "SLC25A28 (mitoferrin-2), which mediates iron uptake in mitochondria, displayed GOF-GI with MEMO1, its knockdown selectively suppressing proliferation of MEMO1-overexpressing breast cancer cells." (PMID 38640016, 2024).
breast carcinoma (continued). "(D) MEMO1 knockout in breast cancer cells M67-9 results in perinuclear mitochondrial clustering in the presence of iron chelator deferoxamine (DFX)." (PMID 38640016, 2024). "The copper chelator tetrathiomolybdate (TTM) treatment hinders breast cancer metastasis by lowering Cu2+ levels and suppressing Mediator Of Cell Motility 1 (MEMO1) expression and angiogenesis." (PMID 38339263, 2024). "Conversely, knockdown or knockout of MEMO1 in breast cancer cells resulted in a statistically significant decrease in the expression levels of TFR1, TFR2, ACO1, and SLC25A28." (PMID 38640016, 2024). "Taken together, these results suggest that MEMO1 knockout increases ferroptosis resistance in breast cancer cells through the reduced iron pool and a higher tolerance toward lipid oxidation products." (PMID 38640016, 2024). "(A, B) Correlations between the expression levels of MEMO1 and selected iron-related proteins in multiple breast cancer (A) and melanoma (B) cell lines as measured by Spearman’s rank-order correlation coefficient." (PMID 38640016, 2024). "This makes MEMO1 a potential therapeutic target in HER2+ breast cancer and, importantly, in TNBC, where few effective treatment options exist, and patient survival is poor." (PMID 38640016, 2024). "(F) Malondialdehyde assay shows lower rates of lipid oxidation in the breast cancer cells with high-MEMO1 expression (WT) compared to cells with MEMO1 knockout (KO) and knockdown (KD) cells." (PMID 38640016, 2024). "Breast cancer cells with MEMO1 knockdown and knockout have significantly higher levels of lipid oxidation product malondialdehyde (MDA)." (PMID 38640016, 2024). "Analysis of the gene expression levels in multiple breast cancer cell lines revealed weak but statistically highly significant correlations between the levels of MEMO1 and TFR1 (p=4.6E-18), TFR2 (p=1.8E-14), and PLOD1 (p=1.8E-33)." (PMID 38640016, 2024). "Knockdown of MEMO1 expression reduces breast cancer cell migration in culture, and significantly suppresses lung metastasis in a xenograft model." (PMID 38640016, 2024). "(E) MEMO1 knockout in breast cancer (M67-9) increases resistance to the ferroptosis inducer RSL3, compared to the parental cell line MDA-MB-231." (PMID 38640016, 2024). "MEMO1 knockout results in a decreased cytotoxicity of RSL3 in breast cancer cells, indicating that high-MEMO1 cells are more sensitive to ferroptosis." (PMID 38640016, 2024). "Since most of the previous work on MEMO1 and its role in cancer was done in breast cancer cell lines, we analyzed the breast cancer and pan-cancer datasets separately." (PMID 38640016, 2024). "Relationship between the expression levels of MEMO1 and iron-related proteins in breast cancer and melanoma." (PMID 38640016, 2024). "Treatment with the copper chelator tetrathiomolybdate (TTM) reduces Cu2+ levels, decreases MEMO1 expression, delays angiogenesis, and inhibits breast cancer cell invasion and metastasis." (PMID 37427098, 2023). "Although only indirect evidence of in-cell interaction, proximity studies in breast cancer cells show Memo1 and Atox1 to be spatially close." (PMID 36067318, 2022). "To link the in vitro interaction data to cells, we used a proximity ligation assay (PLA) to test for Atox1 and Memo1 proximity in breast cancer cells." (PMID 36067318, 2022). "Accordingly, in our hands, silencing of the Memo1 gene in breast cancer cells reduced wound healing ability (a measure of cell migration)." (PMID 36067318, 2022). "Complementary proximity ligation experiments in MDA-MB-231 breast cancer cells imply interactions of Atox1 and Memo1 in living cells." (PMID 36067318, 2022). "Along with ERBB2, MEMO1 was identified to complex with Phospholipase C γ (PLCγ )—an additional signaling molecule downstream of activated ERBB2—in breast cancer cells treated with HRG." (PMID 33172038, 2020).
breast carcinoma (continued). "This interaction occurred downstream of both HRG and E2 stimulation, suggesting MEMO1 as a compelling link between growth factor and steroid signaling, specifically in the context of breast cancer." (PMID 33172038, 2020). "While the studies above were largely conducted in breast cancer cell lines, MEMO1′s integration with ROS-based mechanisms was further extended in vivo, including both in C. elegans and mice." (PMID 33172038, 2020). "In vivo impacts were formally demonstrated using xenograft models, in which human breast cancer cell lines—targeted for MEMO1 knockdown—were subsequently injected into immunocompromised mice." (PMID 33172038, 2020). "Further supporting this interaction, MEMO1 and IGF1R protein expression correlated amongst various breast cancer cell lines and MEMO1 was localized to the cell membrane upon IGF-I stimulation." (PMID 33172038, 2020). "Similar to HRG, upon Fibroblast Growth Factor 2 (FGF2) stimulation, cellular motility—of a breast cancer cell line—was reduced after siRNA-mediated knockdown of MEMO1, relative to controls." (PMID 33172038, 2020). "While most of these studies were conducted in breast cancer cell lines, more recent evidence suggests MEMO1′s regulation of actin and microtubule networks likely extends into other systems." (PMID 33172038, 2020). "These three histidines, which are present in the C. elegans protein, are required for copper binding, and for Memo1’s copper-reducing activity in breast cancer cells." (PMID 28085666, 2017). "Mediator of ErbB2 driven cell motility (Memo1) has been shown to play an important role in migration of breast cancer cells and is needed for robust metastatic dissemination from primary tumors to lungs." (PMID 28085666, 2017). "Mediator of ErbB2-driven cell motility, Memo (gene name MEMO1), is a small ubiquitous redox-active protein with an important role in breast cancer cell migration, invasion, and metastasis downstream of growth factor signaling." (PMID 27472465, 2016). "MEMO1 knockout changed mitochondrial morphology and iron content in breast cancer cells." (PMID 40278406, 2025). "Thus, MEMO1 can serve as a critical link between iron metabolism and metastasis, particularly in breast cancer." (PMID 40278406, 2025). "Importantly, MEMO1 appears to promote cancer metastasis, particularly breast cancer by regulating microtubule dynamics and enhancing lamellipodia formation, thereby enabling cancer cells to migrate into surrounding tissues." (PMID 40278406, 2025). "The contribution of MEMO1 to carcinogenesis is mediated through interactions with the insulin receptor substrate protein 1 pathway and extranuclear estrogen receptor signaling in breast cancer." (PMID 40278406, 2025). "Thus, MEMO1 emerges as a direct molecular link between iron metabolism and metastasis in breast cancer." (PMID 38640016, 2024). "(E, F) Levels of the selected iron-related proteins at various MEMO1 expression levels in breast cancer (E) and melanoma (F) detected by western blot analysis in control (shRNA against the red fluorescent protein) and with the shRNA targeting the gene of interest." (PMID 38640016, 2024). "GIs of MEMO1 may be targeted to suppress metastasis in breast cancer and other malignancies with high-MEMO1 expression level." (PMID 38640016, 2024). "Importantly, MEMO1 is overexpressed in many types of cancer and was shown to modulate breast cancer metastasis through altered cell motility." (PMID 38640016, 2024). "Although it remains to be determined, whether a similar pathway exists in breast cancer cells that we studied, our data provide the first indication that MEMO1 and TFR2 may interact in the iron transport to mitochondria." (PMID 38640016, 2024). "ACO1, SLC25A28, and PLOD1 showed GOF interactions with MEMO1 in breast cancer cells." (PMID 38640016, 2024). "Thus, TFR2 and SLC25A28 (mitoferrin-2) levels are markedly decreased in breast cancer cells with MEMO1 knockdown and knockout." (PMID 38640016, 2024).
breast carcinoma (continued). "MEMO1 knockdown and knockout also decreased overall rates of breast cancer cell proliferation." (PMID 38640016, 2024). "Studies have shown that MEMO1 promotes breast cancer cell invasion and metastasis." (PMID 37427098, 2023). "In support of biological relevance, we show that the cytoplasmic Cu chaperone Atox1, which delivers Cu(I) in the secretory pathway, can interact with and exchange Cu(I) with Memo1 in vitro and that the two proteins exhibit spatial proximity in breast cancer cells." (PMID 36067318, 2022). "In addition to the context of breast cancer metastasis, it is clear that Memo1 has functions in additional cancer cell types, in developmental processes during embryogenesis, and in the homeostatic regulation of adult organ systems." (PMID 36067318, 2022). "MEMO1 (human nomenclature used throughout) was originally discovered through its ability to bind one of these ‘docking’ sites on the erythroblastic oncogene B (ERBB2) receptor within a human epithelial breast cancer cell line." (PMID 33172038, 2020). "Breast cancer cells that lack Memo1 fail to migrate upon stimulation with growth factors." (PMID 28085666, 2017). "During the migratory process Memo1 interacts with Rho GTPase to dynamically reorganize actin and microtubule fibers, and has also been linked to NADPH oxidase activity in breast cancer cells." (PMID 28085666, 2017). "With respect to molecular mechanistic studies of Cu proteins’ roles in breast cancer, there is such information reported for ten proteins and below we discuss findings for selected proteins of the ten (MEMO1, SPARC, LOX, and some LOX-like proteins), followed by a separate section about ATOX1." (PMID 28425924, 2017). "Melanoma cells show much smaller MEMO1-dependent variations in the MDA level than breast cancer cells, consistent with the observed smaller difference in RSL3 sensitivity between the wild type and MEMO1 knockout in melanoma." (PMID 38640016, 2024). "In fact, in our experiments, high-MEMO1 breast cancer cells were significantly more sensitive to the ferroptosis inducer RSL3 and to increased iron concentrations in the medium than MEMO1 knockouts." (PMID 38640016, 2024). "In this respect, MEMO1 was reported to act at the intersection between growth factor (heregulin and IGF1) and estrogen signaling in breast cancer cells." (PMID 28425924, 2017). "We specifically focus on how copper-binding proteins such as mediator of cell motility 1 (MEMO1), LOX, LOX-like proteins, and secreted protein acidic and rich in cysteine (SPARC) modulate breast cancer from molecular and clinical aspects." (PMID 28425924, 2017). "As already mentioned in the previous section, MEMO1 facilitates tumor cell migration, metastasis, and pathways related to EMT, and these results were obtained using breast cancer cells." (PMID 28425924, 2017). "(A, B) Iron levels in the cytosolic (A) and mitochondrial (B) fractions from breast cancer cells with high (parental, WT), low (knockdown, KD), and no (knockout, KO) MEMO1 expression." (PMID 38640016, 2024). "GIs between MEMO1 and PLOD1 in breast cancer cells that we found are particularly notable." (PMID 38640016, 2024). "Like TFR1, shRNA knockdown of HSPA9 results in a major proliferation inhibition of breast cancer and, particularly, of melanoma cells, regardless of MEMO1 expression level." (PMID 38640016, 2024). "By comparison, breast cancer cells with MEMO1 knockout or knockdown show no proliferation rate change in response to TFR2 shRNA knockdown, indicating that TFR2 has a GOF-GI with MEMO1." (PMID 38640016, 2024). "Selective activation of high-MEMO breast cancer cell proliferation by TFR2 knockdown and a marked decrease in cytosolic iron concentration in the context of MEMO1 knockout suggest an important role for MEMO1 in maintaining iron homeostasis in cancer cells, likely in conjunction with TFR2." (PMID 38640016, 2024).
breast carcinoma (continued). "Following MEMO1′s isolation from this phosphorylated residue, it quickly became apparent—utilizing breast carcinoma cell lines—that the cellular machinery required for cell migration, initiated by ERBB2 signaling, was defective when cells were depleted of MEMO1." (PMID 33172038, 2020). "Beyond expression, protein localization also appears to be important as elevated cytoplasmic MEMO1 (as opposed to nuclear) correlated with more unfavorable parameters in breast cancer patients." (PMID 33172038, 2020). "For example, a breast cancer tissue microarray revealed, while normal breast tissue had little to no MEMO1 protein expression, >40% of cancer tissue had increased protein expression levels." (PMID 33172038, 2020). "Specifically, MEMO1 was found to control estrogen receptor α (ERα) sub-cellular localization, phosphorylation, and function downstream of ErbB2/ER or IGFIR/ER thereby activating MAPK and PI3K signaling pathways that promoted breast cancer cell migration and/or proliferation." (PMID 28425924, 2017). "Remarkably, ACO1 knockdown only inhibited proliferation of the high-MEMO1 cells, but not MEMO1 knockout breast cancer cells, while SLC25A28 and PLOD1 knockdowns showed some effect in all cell lines, but a stronger inhibition in the high-MEMO1 cells than in MEMO1 knockout." (PMID 38640016, 2024).